IL17A (interleukin 17A)
Diseases named in the same sentence as IL17A in open-access papers (continued):
Sharing a sentence is not in itself a finding about the gene and the disease.
Sepsis (continued). "Using a TargetScan bioinfomatics analysis that concentrated on miRNAs upregulated in the intestinal epithelial EVs during sepsis, we examined those miRNAs predicted to target TNF-α, and IL-17A." (PMID 33182773, 2020). "Second, this study was designed to strengthen the role of IL17A/IL17-R in the initiation of microglia activation during SAE; hence, we selected an early time point (before sepsis) to modulate the IL-17/IL-17R pathway." (PMID 31686986, 2019). "Thus, AnxA2 may mitigate the severity of sepsis by modulating ROS and IL-17A levels." (PMID 27389701, 2016). "Taken together, our data show that CLP-induced polymicrobial sepsis resulted in SA-AKI, the severity of which was reduced by IL-17A knockout." (PMID 27334720, 2016). "Studies have reported that IL-17A reached high levels in septic mice after cecal ligation and puncture (CLP) injury, and that the use of antibodies to neutralize IL-17A improved sepsis survival from 10 % to nearly 60 %." (PMID 27334720, 2016). "In our sepsis model, dendritic cells expressing TLR2 were required for a robust IL-17A response, which was mediated by IL-1β and IL-23." (PMID 26039416, 2015). "During polymicrobial sepsis after cecal ligation and puncture in C57BL/6 J mice the neutralization of IL-17A by antibody was protective by reducing bacteremia, systemic levels of proinflammatory cytokines/chemokines and improving survival." (PMID 23369364, 2012). "Early sepsis disease 12 h post-infection was characterized by cytokine storm, with concentrations of IFN-γ, CCL2, IL-6, IL-17A, IL-1α, IL-10 and M-CSF significantly elevated in multiple tissues up to 7 days post-infection when mice had recovered from objective clinical measures of disease." (PMID 41910926, 2026). "This peritoneal vicious cycle that includes NET formation, IL-17A, CXCL-1/CXCL-2 that may amplify organ injury in sepsis." (PMID 41041553, 2025). "The observed pattern mirrors the biphasic immunopathology seen in sepsis, where MASLD patients exhibited higher baseline levels of IL17A, IL-23, IL-33, CXCL10 and TGF-β1, yet experienced steeper declines in in IL-10, IL-23, CXCL10 and TGF-β1 in comparison to non-MASLD counterparts." (PMID 40869413, 2025). "Additionally, the levels of pro-inflammatory cytokines, such as IL-17A, IL-6, and TNF-α, were notably elevated in the Sepsis+shPIMI group, whereas the anti-inflammatory cytokine IL-10 was reduced." (PMID 39108261, 2024). "We found that in neonatal lung, intestine and kidney, where DEL-1 was not suppressed in CS sepsis, a higher IL-10 to IL-17A ratio was observed." (PMID 38263289, 2024). "Similarly, a mucosal-route S. aureus nanoemulsion vaccine in previous studies induced strong mucosal and systemic immune responses with high sIgA, IL-17A, and IFN-γ levels and displayed strong protective effects in sepsis and pneumonia models." (PMID 36723073, 2023). "It was discovered that more than 40% of the IL-17A+ lymphocytes were TCRδ+, but only about 10% were TCRβ+ in CLP mice, indicating that hepatic γδ T cells comprise the major subset for IL-17A secretion in sepsis-induced liver injury." (PMID 37475963, 2023). "Additionally, the plasma levels of IL-1Ra, IL-17A, CCL19, CX3CL1, and TNF were significantly higher in septic patients compared to the non-sepsis group." (PMID 37691028, 2023). "For the pro-inflammatory cytokines, except for IL-17A and GM-CSF, which had comparable levels between the malaria and non-malaria sepsis group, significantly lower levels of pro-inflammatory cytokines were found for the children in the sepsis group." (PMID 35811678, 2022). "Additionally, in terms of these indexes in discriminating sepsis deaths from sepsis survivors, PBMC MALT1 disclosed a similar value as Th1 cells, IFN‐γ, Th17 cells, and IL‐17A did, while these values were numerically inferior to APACHE II score and SOFA score." (PMID 35262976, 2022).
Sepsis (continued). "At present, numerous studies have confirmed the important role of IL-17A in sepsis, but the role of secukinumab in sepsis has not been studied." (PMID 36253831, 2022). "Besides, Th1 and Th17 cells were measured in PBMCs from sepsis patients by flow cytometry; interleukin 17A (IL‐17A) and interferon gamma (IFN‐γ) were determined in serum from sepsis patients by ELISA." (PMID 35262976, 2022). "Thus, Therefore, their subsequent studies found that IL-17A can activate NLRP3, which leads to pyroptosis in pneumonia-induced sepsis." (PMID 36349316, 2022). "In this study, we demonstrate that sepsis-induced NMU acting through NMUR1 on lung ILC2s initiates the ILC2 activation, which, in turn, promotes IL-17A-producing γδ T cell expansion and secretion of IL-17A." (PMID 33995408, 2021). "The results of the present study were consistent with previous reports, in that IL-6, IL-8, MCP-1, G-CSF, IFN-γ, and TNF-α were higher than in healthy subjects, but IL-18 and IL-17A were not significantly different between healthy subjects and sepsis patients." (PMID 34654467, 2021). "In this study, using a mouse sepsis model induced by CLP, we show that NMU acting through NMUR1 on lung ILC2s initiates the ILC2 activation, which, in turn, promotes IL-17A-producing γδ T cell expansion and IL-17A secretion." (PMID 33995408, 2021). "Among the six cytokines that differed significantly between the sepsis and FMF groups, GM-CSF, VEGF, FGF-2, and IL-17A were significantly increased in the FMF group compared with the control group, and TNF-α and MIP-1β were significantly higher in the sepsis group than in healthy subjects." (PMID 34654467, 2021). "In addition, serum cytokine levels of IL-1β, IL-6, IL-8, IL-10, IL-12, IL-17A, IL-18, IFN-γ, TNF-α, and calprotectin were found to be elevated in sepsis." (PMID 34654467, 2021). "Indeed, IECs are known to produce both TNF-α and IL-17A, which are critical players in the pathogenesis of sepsis although other sources of TNF-α (macrophages, fibroblasts) and IL-17A (γδ T cells, ILC3) exist especially in the inflamed gut mucosa." (PMID 33182773, 2020). "MAIT cells of WT mice expressed lower levels of IFN-γ and IL-17a during sepsis compared to sham surgery, changes not seen in non-MAIT T cells." (PMID 33164745, 2020). "Furthermore, we demonstrated that targeting IL-17A partially rescued the motility of the small intestine and alleviated interstitial cells of Cajal (ICC) injury during sepsis." (PMID 31531179, 2019). "In conjunction with IL-23 signaling, IL-17A increases the recruitment of neutrophils and their accumulation in the lung following CLP, partially explaining the inflammation seen in the lung following polymicrobial sepsis originating in other tissues." (PMID 31507598, 2019). "Elevated plasma levels of IL-17A may also occur in the context of bacterial sepsis, as described for a cecal ligation and puncture (CLP)-induced polymicrobial sepsis in mice." (PMID 28820494, 2017). "In this sepsis model, other "innate" cells like ILCs and NK/NKT cells, monocytes and even neutrophils may produce IL-17A." (PMID 27389701, 2016). "Since Th17 cells are not the only source of IL-17A, further studies are required to clarify the roles of IL-17A-producing cells in sepsis." (PMID 26693207, 2015). "Our results indicated that the percentage of IL-17A-expressing Th cells in the blood was not affected by sepsis, although IL-17A mRNA expression was downregulated in the spleen." (PMID 26693207, 2015). "More recently, IL-17A-cre reporter mice were developed to permanently mark cells that have activated the IL-17A locus, thus facilitating fate-tracking, and an IL-17A-eGFP knockin mouse was used to track Th17 cells during tolerance induced by a CD3-specific antibody and in mouse models of sepsis." (PMID 22768117, 2012).
Sepsis (continued). "Studies on IL-17A in sepsis has centred on elucidating its role using caecal ligation and puncture (CLP), the most frequently used and clinically relevant model for investigating the complex molecular mechanisms of sepsis." (PMID 23056325, 2012). "ILC2s are not the major source of IL-17A in the lung in sepsis." (PMID 33995408, 2021). "However, it was unknown whether ILC2s secrete IL-17A during sepsis, although it has been reported that in allergic conditions ST2+ nILC2s secrete IL-17A." (PMID 33995408, 2021). "Thus IL-17A may contribute to sepsis progression, like IL-33 and CRTH2, which are potential therapeutic targets for polymicrobial sepsis." (PMID 27389701, 2016). "A number of studies have demonstrated that many promising agents are effective on controlling animal sepsis, including low doses of corticosteroids, LPS-target agents and blockers of inflammatory molecules, as well as anti-HMGB1 (high mobility group box 1) antibody and anti-IL-17A antibody." (PMID 27389701, 2016). "However, the role of IL-17A in sepsis-induced cardiac dysfunction is not clear." (PMID 33981320, 2021). "Compared to wild-type or isotype control treated mice, transgenic mice lacking IL-17A or wild-type mice that received antibody-mediated receptor blockade of IL-17A through IL-17A receptor or cytokine neutralizing antibodies exhibited markedly reduced mortality to sepsis." (PMID 28224121, 2017). "This study suggests that opioid administration will increase the risk of mortality associated with sepsis in ICU patients, and neutralization of IL-17A might be a novel strategy to control excess inflammation and improve survival in septic ICU patients who are receiving opioids for pain management." (PMID 26039416, 2015). "IL-1beta, IFN-α2, IFN-γ, TNF-α, IL-8, IL-33, IL12p70, IL-17A, and IL-23 do not show significant differences between the sepsis groups or compared to healthy controls at d0, suggesting these markers may not play a central role in distinguishing between sepsis types." (PMID 40510342, 2025). "The negative interactions for the sepsis group were between CCL5 and CXCL9, CCL5 and IL-5, and IL2R and IL-17A." (PMID 35811678, 2022). "MALT1 expression was positively correlated with Th17 cells (rs = 0.291, p = 0.038) and IL‐17A (rs = 0.383, p = 0.001), but not with Th1 cells (rs = 0.204, p = 0.151) or IFN‐γ (rs = 0.175, p = 0.125) in sepsis patients." (PMID 35262976, 2022). "MALT1 expression was positively correlated with Th17 cells and IL‐17A, but not with Th1 cells or IFN‐γ in sepsis patients." (PMID 35262976, 2022). "No IL-17A induction was observed in placebo or morphine-treated CLP TLR2KO animals, strongly implying that TLR2 plays a role in IL-17A responses in CLP-induced sepsis." (PMID 26039416, 2015).
Crohn disease (232 papers, 2009 to 2026). A gastrointestinal disorder characterized by chronic inflammation involving all layers of the intestinal wall, noncaseating granulomas affecting the intestinal wall and regional lymph nodes, and transmural fibrosis. "Inflamed mucosal tissues and inflammatory diseases of the gut [inflammatory bowel diseases (IBDs) and Crohn’s disease (CD)] were associated with increased frequency of IFN-γ/IL-17A-producing ILCs and reduced frequency of IL-22-producing ILCs." (PMID 34804991, 2021). "This has been shown to be important clinically: monoclonal antibody against IL-17A, secukinumab, is ineffective in treating Crohn's disease but causes a higher rate of adverse events and increases disease severity." (PMID 31886308, 2019). "Different expression of IL-17A in patients with Crohn’s disease and ulcerative colitis may be associated with the fact that these diseases differ in some aspect of pathogenesis." (PMID 32724117, 2020). "Blocking of IL-17A by Ab treatment leads to more chemokine expression, followed by more immune cell infiltration, resulting in exacerbation of Crohn’s disease." (PMID 40749055, 2025). "The expression of mRNA encoding inflammatory cytokines (IL2, IL17A, IL17F, IL22, IFNG, TNF, CSF2 and LTA) in CD4+ TRM cells was comparable between healthy controls and patients with Crohn’s disease." (PMID 40050432, 2025). "Th17 cells are also implicated in intestinal inflammation, infiltrating the gastrointestinal mucosa of Crohn’s disease and ulcerative colitis patients, leading to excessive IL-17A release." (PMID 38675965, 2024). "In turn, high levels of serum interleukin (IL)-6, IL-17A, IL-23, and interferon-γ are commonly observed Crohn’s disease patients, especially when they are at the active state of the disease." (PMID 38246944, 2024). "Two-phase II trials testing IL-17A-inhibitor agents in patients with Crohn’s disease were terminated due to increased occurrence of adverse events as well as an increased disease activity in the treatment group compared to the placebo group." (PMID 38060157, 2024). "Tissue resident CD4+ T cells are expanded in the mucosa of Crohn's disease patients and more avidly produce IL-17A and TNFα relative to controls." (PMID 37456566, 2023). "A recent study identified FOXP3 +IL-17A+ Treg cells in the intestinal lamina propria of Crohn’s disease patients." (PMID 37615438, 2023). "There is a warning in the prescribing information for IL-17A antibodies for patients with IBD, and active Crohn’s disease is a contraindication to the use of the IL-17 antibody brodalumab." (PMID 38029150, 2023). "Compared to Crohn's disease, the colonic mucosa samples in UC patients showed the expansion of IL17A+ CD161+ effector memory T cells and IL17A+ T-regulatory cells, expansion of HLA-DR+CD56+ granulocytes, and reductions in type 3 innate lymphoid cells." (PMID 35705632, 2022). "In order to observe the effects of moxibustion and acupuncture on the expression of IL-17A and IL-22 in Crohn's disease rats, Liu established the Crohn's disease model with 2,4,6-trinitrobenzene sulfonic acid (TNBS)." (PMID 35075366, 2022). "Nevertheless, treatment of secukinumab, an antibody to IL17A, was ineffective for Crohn’s disease and had severe side effects." (PMID 34390759, 2021). "An anti-IL-17A monoclonal antibody tested as treatment for Crohn’s disease appeared to nevertheless enhance inflammation in a considerable number of patients." (PMID 34210024, 2021). "Further, a recent study examined the intestinal biopsy samples from axSpA patients who developed clinical Crohn’s disease after IL-17A inhibition, and found an expansion of IL-17E producing cells." (PMID 34539646, 2021). "For patients with either Crohn’s disease or UC, Th17 cells are abundant in inflamed intestine terminal ileum and produce IL17A, IL17F, IL26 and IFNγ." (PMID 34390759, 2021).
Crohn disease (continued). "On the contrary, in the advanced lesions of Crohn’s disease, marked up-regulation of IL-17A and induction of IL-23 and IL-6 were observed." (PMID 31941937, 2020). "Despite these limitations, our study provides a better understanding of the possible mechanisms underlying unresolved intestinal inflammation in the presence of anti-IL-17A therapy in Crohn’s disease." (PMID 31941937, 2020). "In this article, we outlined a potential mechanism by which the unexpected results of anti-IL-17A therapy in Crohn’s disease can be explained, and we suggested potential treatment targets." (PMID 31941937, 2020). "Anti-TNFα therapy up-regulated IL6 and IL23p19, in patients with Crohn’s disease; IL-1B and IL17A remained up-regulated in patients refractory to anti-TNF α." (PMID 33193322, 2020). "In patients with Crohn’s disease, IL-17A-producing cells are highly prevalent in the intestinal mucosa, and intestinal mucosal cells exhibit high transcript expression levels of IL-17A1,2." (PMID 31941937, 2020). "Neutralization of IL-17A was even shown to be ineffective at curing patients with moderate to severe Crohn’s disease." (PMID 31275292, 2019). "The unexpected failures of anti-IL-17A in Crohn's disease and of anti-IL-23 in AS are stark reminders of our limited understanding of the pathogenic mechanisms of these diseases and are a call to action to all of us in the biomedical research community." (PMID 30941119, 2019). "For T cells, we evaluated IFN-γ and IL-17A production in CD4+ T cells, as both have been implicated in Crohn's disease pathology." (PMID 28892060, 2017). "Very interestingly, a human anti-IL-17A monoclonal antibody to treat Crohn's disease showed that blockade of IL-17A in humans was ineffective and higher rates of adverse events were noted compared with the placebo group." (PMID 25364738, 2014). "This could be explained by the fact that intestinal inflammation in Crohn’s disease starts in the mucosal secretion of IL-8 and IL-17A, which can be found in significant amounts in blood as inflammation progresses with time." (PMID 36405740, 2022). "Detection of circulating double-positive FOXP3+IL-17A+ CD4+ T cell subsets supports that T cell plasticity may reflect the inflammatory context of Crohn’s disease." (PMID 36405740, 2022). "However, blocking IL-17A or IL-17RA is ineffective or even harmful in the treatment of Crohn's disease." (PMID 35528611, 2022). "For Crohn’s disease, it is surprising that IL-17A blockade is not only ineffective, but may potentially worsen disease activity and/or cause serious side effects." (PMID 34539646, 2021). "In contrast, in classic Crohn’s disease patients, the expression of IL-17E were reduced, and the reduction correlated with endoscopic severity, suggesting IL-17E, similar to IL-17A, might be protective in patients with Crohn’s disease." (PMID 34539646, 2021). "Blocking the function of IL-17A may upregulate Il6 and recruit RORγt+ ILCs in chronic colitis, thereby upregulating IL-22 and worsening the clinical outcomes of patients with Crohn’s disease." (PMID 31941937, 2020). "Fecal IL-17A has also been observed in patients with active Crohn’s disease." (PMID 31941937, 2020). "In order to prevent this unintended response of ILC, simultaneous blocking of IL-17A and IL-6 may be considered as a potential strategy in the treatment of Crohn’s disease." (PMID 31941937, 2020). "If anti-IL-17A therapy affects not only fungi but also the gut microbiome, this may increase disease activity of Crohn’s disease." (PMID 31941937, 2020). "However, initial trials of anti-IL-17A therapy for Crohn’s disease has yielded disappointing results." (PMID 31941937, 2020). "We hypothesized that innate immunity influences the response to anti-IL-17A therapy for Crohn’s disease, since RORγt+ ILCs are primarily distributed in the intestine rather than the skin or joints." (PMID 31941937, 2020).